SPI1 (Spi-1 proto-oncogene)
Diseases named in the same sentence as SPI1 in open-access papers (continued):
Sharing a sentence is not in itself a finding about the gene and the disease.
cancer (98 papers, 2008 to 2026). A tumor composed of atypical neoplastic, often pleomorphic cells that invade other tissues. "In recent years, SPI1 has been proved to be associated with the poor prognosis of multiple cancer types through disordering the immune processes and cell cycle." (PMID 40424327, 2025). "SPI1, a microglial marker gene located on a well-known AD risk locus, was be a part of transcriptional misregulation in cancer pathway, most likely regulating the microglial inflammatory response in AD65." (PMID 38410465, 2024). "SPI1 encodes PU.1, a transcription factor that has been found to be involved in the progression of various cancer types." (PMID 35406439, 2022). "The SPI1 transcription factor regulates alternative transcription of target genes, and both Hltf and SPI1 are frequently mutated in paediatric cancers." (PMID 33603167, 2021). "Forced expression or silencing of SPIB rescued the changes in proliferation and invasiveness of cancer cells caused by SPI1 knockdown or over‐expression." (PMID 34841706, 2021). "SPI1 encodes PU.1, a transcription factor that has been found to be involved in progress in various cancer types." (PMID 33133131, 2020). "The epigenetic upregulation of the proto-oncogene SPI1 and the Osteoclast Associated Ig-Like Receptor (Oscar) are also significant findings for this cancer type samples as upregulation of these genes would promote bone invasion of cancer cells." (PMID 33133131, 2020). "ARID1A was highly expressed in cancer cell and fibroblasts, POU2F2 was significantly expressed in cancer cell, and SPI1 was highly specific to myeloid cell, suggesting its involvement in immune regulation." (PMID 40396172, 2025). "For rs2070721, rs3740688 and rs4788115, the allele that increased cancer risk also increased expression of IRF1, SPI1 and LAT, respectively, in the eQTLGen data." (PMID 40428397, 2025). "As a transcription factor, SPI1 can be recruited by the small nucleolar RNA host gene 16 to regulate downstream gene expression, thereby promoting the biological behavior of cancer cells." (PMID 39062086, 2024). "Intriguingly, the regulation of SPI1 on the transcription of molecular substrates in several cancer cases has been reported to involve lncRNAs." (PMID 36688997, 2023). "As an oncogenic factor that mediates cell carcinogenesis, SPI1 plays a crucial role in the occurrence and deterioration of cancer." (PMID 36967718, 2023). "Activation of SPI1 has been shown to promote glycolysis in cancer cells, which in turn induces neutrophil N2 polarization through lactate, a glycolytic metabolite." (PMID 37539493, 2023). "The transcription regulation of SPI1 on the downstream targets in several cancer cases has been reported to involve lncRNAs." (PMID 36688997, 2023). "As a conserved and immune-related network across multiple cancer types, some molecules in the SPI1-TYROBP(i.e., KARAP or DAP12)-FCER1G network have been identified as prognostic biomarkers before in other cancer types and OS." (PMID 35078433, 2022). "In NB4 cancer cells, the combination treatment led to a stronger down-regulation of SPI1 in the cytoplasmic and nuclear fractions and a more pronounced down-regulation of CEBPE in the cytoplasmic fraction." (PMID 35178376, 2022). "In the present study, multiple databases including ONCOMINE, TIMER, Kaplan–Meier Plotter, and The Cancer Genome Atlas were used to explore the expression levels and prognostic value of SPI1 in GC." (PMID 35237521, 2022). "In a word, SPI1-TYROBP-FCER1G network is a conserved immune-related network underlying both the oncogenesis and the prognosis of OS and other cancer types." (PMID 35078433, 2022). "The transcription factor SPI-1 (Spi-1 proto-oncogene) can participate in cancer progression by regulating the transcription of oncogenes." (PMID 35771155, 2022). "Spearman correlation analysis indicated a strong positive correlation between ACAP1 and SPI1 expression in the TCGA pan-cancer dataset and 28 types of cancer from TCGA." (PMID 36497434, 2022).
cancer (continued). "SPI1 can also be a therapeutic target of cancerous cells, and SPI1 knockdown suppresses aerobic glycolysis and progression of cancer." (PMID 35945192, 2022). "Taken together, these data revealed that SPIB coordinated with SPI1 in driving glycolytic process and progression of cancer." (PMID 34841706, 2021). "Our evidence shows that as a glycolytic metabolite, lactate triggers polarization of N2 neutrophils, which deliver SPI1 mRNA via extracellular vesicles to enhance SPI1 expression of cancer cells." (PMID 34841706, 2021). "Glycolytic capacity and metabolite measurement assays indicated that conditional medium of TANs significantly facilitated glycolytic process of cancer cells, while silencing of SPI1 suppressed these effects in cancer cells." (PMID 34841706, 2021). "We further explored cooperative roles of SPIB and SPI1 in aerobic glycolysis and cancer progression." (PMID 34841706, 2021). "Therapeutic targeting of SPIB/SPI1‐facilitated interplay of cancerous cells and neutrophils suppresses aerobic glycolysis and progression of cancer." (PMID 34841706, 2021). "Collectively, these data revealed that SPI1 promoted cancer progression via facilitating aerobic glycolysis." (PMID 34841706, 2021). "Neutrophils are polarized by SPI1‐facilitated glycolysis, which in turn deliver SPI1 mRNA into cancer cells via extracellular vesicles." (PMID 34841706, 2021). "Mechanistically, neutrophils delivered SPI1 mRNA via extracellular vesicles, resulting in enhanced SPI1 expression of cancer cells." (PMID 34841706, 2021). "To systematically investigate the exon structure of circSPI1, we first used a pan-cancer circRNA compendium MiOncoCirc14 and identified five isoforms of circSPI1s originating from exons 2, 3, and 4 of the SPI1 gene." (PMID 33741901, 2021). "Stable over‐expression or silencing of SPI1 promoted and attenuated the growth and invasion of cancer cells, respectively." (PMID 34841706, 2021). "For investigating the involvement of aerobic glycolysis in SPI1‐promoted tumourigenesis and aggressiveness, glycolysis inhibitor or activator was applied in cultured cancer cells." (PMID 34841706, 2021). "Through physical interaction with SPI1‐related protein (SPIB), SPI1 drove expression of glycolytic genes within cancer cells, which in turn induced polarization of neutrophils via glycolytic metabolite lactate." (PMID 34841706, 2021). "Previously, we showed that deletion of the Spi-2/Spi-1 genes from VV renders it highly-attenuated in normal tissue, yet it retains replication competence in cancer cells and functions as a potent oncolytic VV." (PMID 30626434, 2019). "To date, it has been reported that cytosporone B can be an effective SPI-1 inhibitor in antibiotic-resistant Salmonella and stimulate Nur77-dependent transactivational activity to inhibit cancer cell growth." (PMID 30934892, 2019). "SPI1 (transcription factor PU.1) was shown to be the most significantly enriched transcription factor that regulated the pan-cancer immune gene expression signature." (PMID 30956779, 2019). "As a transcriptional regulatory factor, SPI1 is involved in the progression of various cancers." (PMID 39535362, 2025). "Furthermore, the reason why SPI1-TYROBP-FCER1G network was upregulated in certain cancer types but downregulated in the others including OS, and its potential immunological mechanism, cannot be answered by our study and need further explorations in the future." (PMID 35078433, 2022). "Next, we used Kaplan–Meier Plotter to analyze whether the expression of SPI1 was related to the prognosis of patients with cancer and the extent to which it was related." (PMID 35237521, 2022). "First, we analyzed the expression levels of SPI1 mRNA in different types of cancers." (PMID 35237521, 2022). "In summary, macrophages and T cells with high SPI1 expression levels may interact with cancer cells by secreting chemokines and immune molecules." (PMID 36477668, 2022).
cancer (continued). "Thus, the roles of SPIB/SPI1 in aerobic glycolysis and cancer progression are warranted by further studies using syngeneic mouse models." (PMID 34841706, 2021). "SPIB facilitates SPI1 transactivation via physical interaction in cancer cells." (PMID 34841706, 2021). "Through physical interaction with its homologous partner SPIB, SPI1 is activated to promote aerobic glycolysis of cancer cells via upregulating HK2 or phosphoglycerate kinase 1 (PGK1), which in turn induces N2 polarization of neutrophils via glycolytic metabolite lactate." (PMID 34841706, 2021). "Since pharmacological inhibition of glycolysis or knockdown of target genes abolished the oncogneic roles of SPI1 in tumourigenesis and aggressiveness, our results demonstrate that SPI1 promotes cancer progression through facilitating aerobic glycolysis of cancer cells." (PMID 34841706, 2021). "Validated miR-155 target genes are present in multiple pathways associated with cancer and cancer progression, including EMT (SMAD5), proliferation (SOCS1, INPP5D, and CSF1R), block of differentiation (SPI1, CEBPB), and apoptosis (CASP3, FADD, APAF1, and FOXO3A)." (PMID 27128908, 2016). "We speculate that SPI1 can play a role in promoting cancer through PAICS." (PMID 35361282, 2022). "Furthermore, the transcriptional levels of FCER1G and SPI1 can also distinguish the OS patients into two clusters with different prognosis and immune cell infiltrations, suggesting a potential treatment target for OS and other TYROBP-associated cancers." (PMID 35078433, 2022). "Based on the hypothesis that cancer cells often overexpress multiple anti-apoptotic proteins, and are thus more resistant to apoptosis, we deleted two anti-apoptotic viral genes, SPI-1 and SPI-2, resulting in a highly tumor-selective virus (vSP) that retains oncolytic potency." (PMID 30626434, 2019). "It was found that upon the suppression of LINC01004 or SPI1 and the subsequent SIGLEC9 inhibition, the DNA synthesis ability, and the migration and invasion activities of cancer cells were significantly suppressed, along with increased necrosis rate of cells." (PMID 36688997, 2023). "In the current study, we demonstrate that as a transcriptional activator, SPI1 enriches on promoter regions of glycolytic enzymes HK2 and PGK1 and facilitates their expression in cancer cells." (PMID 34841706, 2021). "Transcription factor SPI1 promotes aerobic glycolysis via upregulating HK2 and PGK1 in cancer cells." (PMID 34841706, 2021). "Among the results, the expression levels of CD34, IL6, SPI1, and SELL showed significant expression differences in 16, 12, 12, and 11 cancer types, respectively, especially in BRCA." (PMID 33869191, 2021). "In the “pathways in cancer”, PIK3R5, SPI1, and CSF1R are most relevant to FPR3 expression (Figures 7A1–A3)." (PMID 33679387, 2020). "The dedifferentiation of cancer cell was inhibited through inhibition of IL-6, CCAAT/enhancer binding protein alpha (CEBPα), Spi-1 proto-oncogene (PU.1), c-Myc and E2F transcription factor 1 (E2F1)." (PMID 30373594, 2018). "Additionally, 46 out of the 49 TFs are known to play roles in CRC and the remaining three (RFXAP, SPI1 and RFX5) are related to other cancers." (PMID 36760999, 2023). "In both of these cancers, most of the 48 marker genes showed a positive correlation with SLC1A5 expression, with the highest correlation being found between SLC1A5 and a T helper cell 9 (Th9) marker PU.1 (SPI1), which is an oncogene." (PMID 34367941, 2021). "In addition, forced or impaired SPI1 expression respectively enhanced or reduced the levels of HK2 and PGK1 in cancer cells." (PMID 34841706, 2021). "Administration of an inhibitory peptide blocking SPIB–SPI1 interaction was efficient in suppressing glycolytic process, tumourigenesis and aggressiveness, indicating the oncogenic activities of SPIB/SPI1 in aerobic glycolysis and progression of cancer." (PMID 34841706, 2021).
cancer (continued). "Mutation of these residues abolished the interaction between SPI1 and SPIB in cancer cells." (PMID 34841706, 2021). "There was increase and decrease in SPI1 enrichment, promoter‐luciferase reporter activity, as well as levels of HK2 and PGK1 in cancer cells stably over‐expressing or silencing SPIB, which was eliminated by silencing or ectopic expression of SPI1, respectively." (PMID 34841706, 2021). "Additionally, analysis of 8 pairs of ccRCC cancer tissues and corresponding adjacent tissues revealed a negative correlation in SPI1 and ACSL4 expression levels." (PMID 41372608, 2025). "Furthermore, we analyzed our original chromatin accessibility data,and found that the DNA binding motifs of ELF1, JUND, and SPI1, which arepotential transcription factors of PARP10, NIPAL1 and ZYG11B in CRC tissues, arespecifically open in cancer tissues compared with adjacent tissues." (PMID 41020586, 2025). "SPI1, as the key transcription factor for the network, may shape a positive-feedback network with the signaling from TYROBP/FCER1G or environmental TNF-α/IFN-γ, then furtherly initiate the whole SPI1-TYROBP-FCER1G network to regulate the immune infiltration and cancer prognosis." (PMID 35078433, 2022). "Interestingly, immunohistochemistry revealed that SPI1 was more highly expressed in TIICs rather than in cancer cells, consistent with the SPI1 expression in renal cell lines." (PMID 36477668, 2022). "Depletion of neutrophils or blocking SPIB–SPI1 interaction significantly suppresses glycolytic process, tumourigenesis, as well as aggressiveness of cancer cells, suggesting that SPIB/SPI1‐facilitated interplay of cancer cells and neutrophils may be a potential therapeutic target for cancers." (PMID 34841706, 2021). "On the other hand, co‐culture with TANs led to increase of SPI1 expression and its enrichment on HK2 or PGK1 promoter in LoVo and HCT116 cells, resulting in increase of HK2 or PGK1 promoter activity and transcript levels, while silencing of SPI1 in cancer cells reduced these effects." (PMID 34841706, 2021). "Validating co‐immunoprecipitation (co‐IP) assay indicated endogenous interaction of SPI1 with SPIB, but not with GATA2, in cultured cancer cells." (PMID 34841706, 2021).
neurodegenerative disease (14 papers, 2020 to 2025). A disorder of the central nervous system characterized by gradual and progressive loss of neural tissue and neurologic function. "The possible role of microglial dysfunction in patients with SPI1 mutation could explain their susceptibility to neurodegenerative diseases thus highlighting the importance of genetic testing in patients with inborn errors of immunity." (PMID 38500873, 2024). "The significant association of these gene lists with metabolism, immune function, and multiple neurodegenerative diseases further establishes the role of SPI1 in AD-related pathology." (PMID 38734693, 2024). "Other genes such as SPI1, LRRC37A, NSF, and TCTA have also been reported to have effect on neurodegenerative diseases." (PMID 39905509, 2025). "In summary, both APP and SPI1 are related to protein homeostasis and even accelerate the development of both T2DM and neurodegenerative diseases (NDs)." (PMID 37293508, 2023).
neurological diseases (6 papers, 2013 to 2025). "Besides that, in this LD block, several variants act as eQTLs/sQTLs in the brain and whole blood, altering the expression of many genes already related to LOAD or other neurological diseases in human or animal studies, such as CELF1 itself, MADD, MYBPC3, NR1H3, NUP160, SPI1, and TOMM40." (PMID 34291080, 2021).
bacterial infection (5 papers, 2009 to 2023). "Besides, SPI-1 effector SipB and SPI-2 effectors are inessential in regulating vimentin rearrangement, which were evidenced by ΔsipB and ΔphoP bacterial infection." (PMID 36717589, 2023).
hematological malignancies (5 papers, 2011 to 2026). "Recent studies have also confirmed the prognostic potential of SPI1 in a variety of solid tumors other than hematological malignancies." (PMID 35237521, 2022).
immune disease (5 papers, 2016 to 2025). "Recently, many researchers have found that PU.1, encoded by the SPI1 gene, affects the differentiation and function of a variety of myeloid cells and plays an important role in the transcriptional control of certain immune cells and susceptibility to immune diseases." (PMID 37226132, 2023).
psychiatric disorder (5 papers, 2020 to 2025). A disorder characterized by behavioral and/or psychological abnormalities, often accompanied by physical symptoms. "Several genes, such as PES1, SPI1, and NSF, exhibit multiple significant associations across different traits, indicating their potential central roles in the genetic network influencing psychiatric disorders." (PMID 39905509, 2025).
cardiac disease (1 paper, 2024). "There is little evidence about what roles SPI1 and FOXA1 play in cardiac disease." (PMID 38994368, 2024).
gastrointestinal disease (1 paper, 2010). A disease that occurs in the gastrointestinal system, excluding the hepatobiliary system. "However, little is known about the role of SPI-1 in mediating gastrointestinal disease in humans." (PMID 21206750, 2010).
hematopoietic cancer (1 paper, 2021). "Another study demonstrated that SPI1, as a transcriptional factor in hematopoietic cancer cells, could directly suppress the expression of METTL14." (PMID 35003212, 2021).
intestinal disease (1 paper, 2024). "SPI-1 allows the bacteria to invade the intestine, while SPI-2 is important for intracellular survival and replication, although it is also necessary for intestinal disease." (PMID 37490241, 2024). "Our results demonstrate the importance of both SPI-1 and SPI-2 genes to produce a complete intestinal disease that subsequently leads to systemic dissemination, and they also show for the first time the exact location of S. Typhimurium through the avian infection." (PMID 37490241, 2024).
SPI1 also shares sentences with these, for which no sentence is quoted: hepatocellular carcinoma (7 papers); anemia (6); myeloproliferative neoplasm (5); rheumatoid arthritis (5); ulcerative colitis (5); Arthritis (4); prostate carcinoma (4); psoriasis (4); brain injury (3); glaucoma (3); Hepatic steatosis (3); inflammation (3); liver cancer (3); multiple myeloma (3); myeloid malignancies (3); neutropenia (3); T-cell lymphomas (3); acute erythroleukemia (2); age (2); allergic rhinitis (2); allergies (2); Anxiety (2); B-cell acute lymphoblastic leukemia (2); brain tumor (2); Diarrhea (2); emphysema (2); follicular lymphoma (2); gastric tumor (2); Granuloma (2); head and neck cancer (2).
A further 134 diseases each share a sentence with SPI1 in 2 papers or fewer.